CDK4 (cyclin dependent kinase 4)
Diseases named in the same sentence as CDK4 in open-access papers (continued):
Sharing a sentence is not in itself a finding about the gene and the disease.
tumor (continued). "Cyclin D (CCND) forms active complexes with CDK4 and CDK6 (CDK4/6), which drives the G1-S phase transition by phosphorylating tumour-suppressor ‘pocket proteins’ retinoblastoma (Rb), p107, and p130." (PMID 37510349, 2023). "Since both RT and CDK4/6 inhibitors elicit cellular senescence as part of their in vivo effects, we hypothesized that the differential efficacy of RT followed by (→) P vs P→RT could depend on the differential accumulation of senescent cells in the tumor microenvironment (TME)." (PMID 36765430, 2023). "In this study, we used Crisper-Cas9 technology to generate Cdk4 and Cdk6 knockout cell lines to elucidate the role of CDK4 and CDK6 in anti-tumor immunity accurately." (PMID 37833461, 2023). "The models showed characteristic copy number variations (CNV) of disease-related genes (e.g., MDM4, EGFR, CDKN2A, CDK4, and MDM2) that were fairly consistent with the primary tumor." (PMID 37508520, 2023). "Inhibition of miR-191 increase PLCD1, and then decrease β-catenin, MMP-9, C-myc, N-cadherin, CDK4 and PCNA, ultimately leading to the decrease of proliferation, migration and invasion of OSCC cells, thus exerting anti-tumor effects." (PMID 37460940, 2023). "dsRNA-mediated down-regulation of CDK4, AKT, and HER2 resulted in the suppression of tumor cell proliferation." (PMID 37615898, 2023). "Starting from our previous study on the comparison of the genomic profiles of matched tumour core and PBZ biopsies, we selected CDK4 and EXT2 as putative malignant drivers of PBZ." (PMID 36769158, 2023). "Surprisingly, both NTRK fusion and MDM2/CDK4 amplification have been undetected after 5-week treatment of NTRK inhibitor, which was confirmed by the NGS testing of the resected tumor sample." (PMID 36652666, 2023). "Keeping in mind that these profiles represent a snapshot of the underlying cancer process, we observed that the expression of CDK1 and CDK4 increased significantly with the tumor’s pathologic stage in KICH (CDK1, p = 1.37 × 10−5 and CDK4, p = 6.39 × 10−3)." (PMID 37047552, 2023). "These inhibitors work by inhibiting CDK4/CDK6-dependent phosphorylation of retinoblastoma (Rb), which blocks proliferation by inhibiting the progression of tumor cells from the G1 phase into the S phase of the cell cycle." (PMID 37760421, 2023). "As an upstream inhibitor of cyclin-dependent kinase 4/6- (CDK4/6-) mediated cell cycle activity, p16INK4a is widely involved in regulating tumor and senescence." (PMID 36852326, 2023). "The expressions of ITPR2, MDM2, KRAS and CDK4 were also highest in the CLDN2+ AT2 cells, and higher in the tumor-derived CLDN2+ AT2 cells than the normal ones." (PMID 37488117, 2023). "Recent studies have shown that combined treatment with the CDK4/6 inhibitor Abe and an oncolytic virus significantly suppresses GBM tumor growth and prolongs the survival of tumor-bearing mice." (PMID 37446710, 2023). "Flow cytometry analysis revealed that there was an increased number of tumor-infiltrating immune cells including CD8+ T cells and DCs in Cdk4−/− tumors compared with the control tumors." (PMID 37833461, 2023). "The dedifferentiated tumour areas showed positive MDM2 and CDK4 staining within neoplastic cells, with the Ki 67 proliferation marker expressed in approximately 10% of the cells." (PMID 37241198, 2023). "CCND1 forms complexes with CDK4 or CDK6 as a regulator of CDK kinases, and its tumor-promoting role has been intensively investigated in human cancers." (PMID 37770914, 2023). "While targeting CDK6 can directly inhibit tumor cell proliferation, we put forward a pathway by which blocking CDK4 and CDK6 in cancer cells enhance anti-tumor immune responses by inducing DNA damage-mediated, STING-dependent type I IFN production." (PMID 37833461, 2023). "After 14 days of preoperative CDK4/6i and endocrine therapy, the expression of the MKS metagene was significantly higher in MKShi/ERSlo compared to MKShi/ERShi tumours (p = 0.015)." (PMID 37935787, 2023).
tumor (continued). "We also found amplifications of CDK4 and MDM2 with PDGFRA gain in the recurrent tumor and upregulated protein expressions of these genes." (PMID 38012788, 2023). "When phosphorylated by cyclin D, cyclin-dependent kinase 4 (CDK4), and CDK6, RB1 will be inactive, resulting in an unregulated progression through the cell cycle and tumor growth." (PMID 36674870, 2023). "Given that ER and progesterone receptor (PR) signaling are major promoters of cyclin D–CDK4/6 activity in HR+ BC cells, it was not unexpected that loss of ER/PR expression was associated with primary resistance to CDK4/6i in BC cell lines and tumor biopsy specimens." (PMID 37835528, 2023). "The immune-modulatory functions of CDK4/6 inhibitors include increasing antigen representation, promoting infiltration of CD45+ cells into the tumor, activating effector T cells and inhibiting Treg proliferation." (PMID 35372020, 2022). "A large number of studies have found that drugs can inhibit the growth of tumor cells by suppressing the expression of cyclins such as CCND1 and CDK4." (PMID 36364084, 2022). "CCND1 (cyclin D1) is one of the regulators of CDK kinases by forming complexes with CDK4 or CDK6 as a subunit, whose tumor-promoting role in the development of human cancers has been intensively investigated." (PMID 35365622, 2022). "When combined with abemaciclib, a CDK4/6 inhibitor, OTX015 induced more potent tumor regression than current standard-of-care treatment of abemaciclib + fulvestrant." (PMID 35881485, 2022). "They developed an inhibitor of cyclin-dependent kinase 4 (CDK4), which can be used for the treatment of various neoplasms due to the overexpression of this kinase in multiple tumor cells." (PMID 35892711, 2022). "Previously, hsa-miR-338-3p was reported to be an OS tumor suppressor that targeted RUNX2 and CDK4 through the MAPK pathway." (PMID 35151325, 2022). "At present, some potentially predictive biomarkers have been found for CDK4/6 inhibitors, such as cyclin E1 (CCNE1), thymidine kinase 1 (TK1) mRNA expression, and circulating tumour DNA (ctDNA)." (PMID 36028895, 2022). "As previously observed in vitro, pladienolide B administration in vivo significantly decreased various relevant tumor progression markers and critical oncogenic spliceosome components (VEGFA/EGFR/CDK4/PDGFRA/PDGFRB and SRSF3/PTBP1)." (PMID 35086552, 2022). "A recent study found that combining abemaciclib, a CDK4/6 inhibitor, with merestinib, a c-MET inhibitor, reduced FOXM1 expression, and significantly inhibited tumor growth in metastatic UM tumors grown in human HGF-knock-in immunocompromised mouse models." (PMID 35954441, 2022). "The expression level of cell cycle‐related proteins, such as cyclin D1, cyclin E, Cdk2, Cdk4, Cdk6, and PCNA was also decreased in anti‐Chi3L1 antibody‐treated lung metastasis tumor tissue." (PMID 34861103, 2022). "Comparing 31 tumour types, UM ranked amongst the tumours with the highest oxidative phosphorylation signature and targeting of MEK and CDK4/6 in UM leads to adaptive upregulation of oxidative phosphorylation." (PMID 36698840, 2022). "Expansion of tumor-specific CTLs is fundamental to the efficacy of ICI, and it is likely this expansion will be somewhat compromised while CDK4/6i is administered." (PMID 35444175, 2022). "Immunohistochemical studies using primary antibodies for MDM2 (clone SMP14, Zeta, dilution 1/230) and CDK4 (clone DCS-31, Zeta, dilution 1/230) revealed that the tumor cells in both components were immunoreactive for CDK4." (PMID 34089125, 2022). "The loss of the AMBRA1 protein drives the tumor formation in mice and is linked with worse outcomes in some human tumors, and they also found that a lack of AMBRA1 may make some tumors resistant to drugs called CDK4/6 inhibitors, which are a promising new class of cancer treatments." (PMID 34901460, 2022).
tumor (continued). "CCND1 is an important cell cycle regulatory protein that promotes the proliferation of cancer cells by forming a cell cycle-dependent complex with cyclin-dependent kinase 4 (CDK4), which contributes to the development of many tumor diseases, including HCC." (PMID 35873910, 2022). "Viral mimicry is thought to be an important mediator of tumor innate immunity in response to epigenetic therapies such as DNMT inhibitors, histone deacetylase inhibitors, CDK4/6 inhibitors and EZH2 inhibitors." (PMID 36923279, 2022). "They suppress proliferation and induce apoptosis in a variety of tumor cells, including GBM, by inhibiting the CDK4/6-cyclin D-Rb-E2F pathway." (PMID 36432068, 2022). "However, CDK4/6 inhibitors, currently approved for the treatment of estrogen receptor- positive breast cancer, displayed mainly a cytostatic effect when administered alone, whereas combination therapies demonstrated an enhanced efficacy in different tumor types." (PMID 36497412, 2022). "In this mouse model, CDK4/6 inhibitors in this mouse model induced the SASP in PDAC cells, increasing vascularity and the immune response in the PDAC tumour microenvironment." (PMID 35674109, 2022). "In contrast, the in-silico drug candidate identification of scAmpi marked the complete tumor population to be potentially sensitive to palbociclib treatment, based on the over-expression of CCND1 and further supported by the expression of CDK4." (PMID 35658001, 2022). "In accordance, PI3K/AKT signal pathway was reported to function momentously in various tumors to induce the resistance of CDK4/6 inhibitors or temozolomide and be involved in ALDH1A3-dependent tumor progression." (PMID 35831872, 2022). "In TCGA cohort, the tumor stage and radical resection were as adjusted factors in the multivariate Cox regression model and regression coefficients (β) of CDK1 and CDK4 were calculated." (PMID 35193513, 2022). "Recently, potent selective inhibitors of CDK4 and CDK6 have been approved for the treatment of advanced BC and are being tested against other tumor types." (PMID 35681689, 2022). "YTHDF1 deficiency regulates the transformation efficiency of cyclin-dependent kinase 2 (CDK2), cyclin-dependent kinase 4 (CDK4), and cyclin D1 (CCND1) through the Keap1-Nrf2-AKR1C1 pathway to inhibit tumour cell proliferation and xenograft tumorigenesis." (PMID 35518355, 2022). "Like CDK4/6i, BRAF and MEK inhibitors (BRAFi + MEKi), which inhibit the MAPK/ERK pathway, were originally developed to block tumor cell proliferation and survival, but were subsequently discovered to augment anti-tumor immunity." (PMID 35444175, 2022). "These tumours express high CDK6 protein levels, and their cell lines were noted to be highly sensitive to CDK6 knockdown, indicating that CDK4/6 inhibitors are good candidates for treatment." (PMID 36077812, 2022). "Downregulation of CDK4/CDK6 in combination with p21 upregulation are major regulators of cell cycle arrest and important for tumor growth reduction." (PMID 35884996, 2022). "Experience with other CDK4/6 inhibitors suggests that promising efficacy signals such as these might be enhanced through rational combinations with AIs, fulvestrant, or antitumor agents with different targets/mechanisms of action (including radiation therapy) suited to the tumor of interest." (PMID 36291780, 2022). "The CDK4 inhibitor palbociclib resulted in favorable PFS and occasional tumor responses in a phase II trial for advanced WD/DDLPS." (PMID 36119484, 2022). "Analysis of genes characterizing tumor cell proliferation and cell cycle activity revealed an upregulation of KI67, MCM3, and CDK4 in Tcam-2 cells cocultured with T cells." (PMID 35269507, 2022). "In vivo, we show that pharmacological FAK inhibition reduced B16F10 tumor size, correlating with increased FAK nuclear localization and decreased CDK4/6 expression compared with vehicle controls." (PMID 35525274, 2022).
tumor (continued). "The correlation between the expression of cell cycle-related genes and immune cells suggested roles for CDK4, CCNB1, CHEK1 and CDKN2A in regulating HCC tumor immunology." (PMID 36403263, 2022). "Mechanistically, a CDK4/6 inhibitor enhanced the secretion of IFN by activating the STING pathway and thus enhanced tumor antigen presentation ability." (PMID 35095879, 2021). "We found that abemaciclib suppressed HCC cell proliferation in vitro and tumor growth in vivo, suggesting that it was an attractive drug for HCC patients, especially those with high CDK4 expression." (PMID 33686022, 2021). "This increased CDK4 degradation, which decreased CDK4 protein levels and inhibited CRC tumor growth." (PMID 33968776, 2021). "For example, the smaller cell cluster B4b was a highly proliferative tumor with cells at either the G2/M, or S phase (right two panels) and displayed high expression of MKI67, CDK4, and other proliferative markers such as PCNA, TK1, and TYMS." (PMID 34001881, 2021). "For instance, a combination of inhibitors to IGFR and CDK4/6 profoundly repressed the PI3K/mTOR pathway and had a synergistic anti-tumor effect in vitro and in vivo in EwS." (PMID 34188019, 2021). "Combination of CDK4 and MEK inhibitors controls syngeneic tumor growth and prevents emergence of EMT-mediated resistance." (PMID 34309585, 2021). "The enhanced inhibition of HIF1α by combined targeting of CDK1 or CDK4/6 and HSP90 was observed in multiple tumor cell lines." (PMID 34686682, 2021). "Regarding EMPD, a recent report suggested that CDK4 and cyclin D1 are overexpressed in EMPD tumor cells." (PMID 34395284, 2021). "Abundant levels of CDK4 are especially observed in CRC patients with enhanced dysplasia and are correlated to increased tumor cell proliferation." (PMID 35002699, 2021). "These drugs have also been shown to inhibit tumor progression by altering the expression levels of proteins related to cell cycle and apoptosis such as CCNE1, CDK4 and BCL-2, and by inhibiting drug efflux pumps." (PMID 35155562, 2021). "Previous studies showed that combinations of radiation or targeted agents, everolimus and altiratinib, with CDK4/6 inhibitors have synergistic effects against GBM cells and tumor growth in vitro and in vivo." (PMID 34885226, 2021). "PI3K-AKT-mTOR and RASRAF-MEK-ERK pathway inhibitors showed synergistic tumor inhibition in many preclinical vitro and vivo models in NSCLC with CDK4/6 inhibitors." (PMID 34395246, 2021). "Because this signaling impacts on the cell cycle, cyclin-D1/CDK4 and CDK6 function, autophagy and IR are involved in many human neoplasms." (PMID 34445095, 2021). "For example, the smaller cell cluster B4b was a highly proliferative tumor with cells at either the G2/M, or S phase and displayed high expression of MKI67, CDK4, and other proliferative markers such as PCNA, TK1, and TYMS." (PMID 34001881, 2021). "Deficiency of YTHDF1 functionally prevents NSCLC cell proliferation and tumor formation through inhibiting the translational efficiency of cyclin-dependent kinase 2 (CDK2), cyclin-dependent kinase 4 (CDK4), and cyclin D1 (CCND1)." (PMID 34359836, 2021). "We found that CDK2, CDK4, CDK6, and STAT3 expressions were higher in tumor cohorts compared to normal cohorts." (PMID 33668805, 2021). "Inhibition of CDK4 and CDK6 can prevent cell cycle progression, prevent tumor growth and promote senescence." (PMID 34395246, 2021). "Accordingly, it has been shown in PDAC cells and in other cancer types, that the co-inhibition of the cyclin D1 interacting kinases, CDK4/6, potentiates the global effects of KRASG12C inhibition, blocking the cell proliferation and inducing tumor regression." (PMID 33670598, 2021).
tumor (continued). "It has been reported that miR-34a can regulate tumor angiogenesis by directly inhibiting angiogenic functions of endothelial cells by downregulating several key proteins including E2F3, SIRT1 and CDK4 in HNSCC." (PMID 33981611, 2021). "For instance, basis 1 contains classic housekeeping genes, such as GAPDH and ribosomal protein genes (RP-); basis 3 contains well-known tumor-related genes, including EGFR and CDK4." (PMID 34252925, 2021). "A Lung-MAP trial (SWOG S1400) demonstrated the amplification of CDK4 or CCND1/2/3 in patients with squamous NSCLC and tumor." (PMID 34395246, 2021). "The literature was reviewed to evaluate the use of liquid biopsy, for the analysis of tumour-derived material, in order to identify predictive biomarkers in HR+/HER2− metastatic BC (mBC) patients that were treated with CDK4/6 inhibitors plus endocrine therapy." (PMID 34068388, 2021). "We investigated the efficacy of ribociclib, a CDK4/6 inhibitor, in combination with cetuximab, a monoclonal antibody targeting the EGFR, in HPV-negative SCCHN patient-derived tumor xenograft (PDTX) models." (PMID 33809148, 2021). "Conversely, an increase in tumor purity was positively correlated with the expression of CDK-1 in COAD due to CD4+cells and CDK-4 in COAD and READ resulting from a fraction of immune cells." (PMID 33732631, 2021). "Our finding of RB1 deletions in 34% of tumours with CDKN2A deletion makes responses to CDK4/CDK6 antagonists less likely and underpins our finding that the CDK4/CDK6 inhibitor Palbociclib had marginal effects on primary cell survival." (PMID 34580349, 2021). "On the other hand, we observed an increased expression of CDK4 and E2F4 in tumor cells isolated from ZF-cluster, genes regulating cell cycle progression." (PMID 34502201, 2021). "These resistant nodules also appeared to exhibit an increase in CDK4 expression, consistent with the Western blot analyses of resistant PDX tumour." (PMID 33179425, 2021). "The following factors were included as explanatory variables: sex, age, tumor site, tumor size, TNM stage, and CDK4/cyclin D1 expression." (PMID 34395284, 2021). "In keeping with the complementary effect of dual targeting CK1ε and CDK4/6 in vitro, addition of CK1ε kinase inhibitor D 4476 dramatically enhanced the efficacy of ribociclib on retarding 4T1 and MDA-MB-231 tumor growth in vivo." (PMID 34508104, 2021). "In this study, we found that the combination of CDK4/6 inhibitor SHR6390 and pan-her inhibitor pyrotinib in HER2+/HR+ cell lines (EFM-192A and BT474) shows synergistic inhibition of tumor proliferation and enhances antitumor effects in vitro." (PMID 34977029, 2021). "Last but not least, evidences accumulated in the last few years highlighted a role for CDK4 and CDK6 inhibition in triggering anti-tumor immunity." (PMID 34204543, 2021). "The overexpression of HOPX, upregulation of p21, and downregulation of cyclin D1 and CDK4 regulate the progress of migration and invasion of MDA-MB-468 cells to modulate tumor growth of the breast." (PMID 34235216, 2021). "Overall, this increases tumor antigen presentation and, together with additional effects of the CDK4/6 inhibitors, leading to cytotoxic T-lymphocytes (CTL)-mediated clearance of the tumor cells in mouse models." (PMID 33668131, 2021). "Our analyses identified drugs targeting CDK4, CDK6 and AURKA as strong candidates for MB; all of these genes are well validated as drug targets in other tumour types." (PMID 34154646, 2021). "In summary, these results demonstrate the efficacy of CDK4 and MEK inhibitors in combination for effective therapeutic targeting of the tumor cell subpopulations." (PMID 34309585, 2021). "The analysis including the cases of tumor in situ revealed that the overexpression of both CDK4 and cyclin D1 in EMPD tumor cells was significantly correlated with worse DSS (HR: 4.76, p = 0.033)." (PMID 34395284, 2021).